CD4 (CD4 molecule)
Diseases named in the same sentence as CD4 in open-access papers (continued):
Sharing a sentence is not in itself a finding about the gene and the disease.
tumor (continued). "More importantly, TS regulated the immunity of H22 bearing mice by elevating the ratio of CD4+ T cells in spleen, and increasing the number of T cell infiltration in tumor tissue." (PMID 35577774, 2022). "A direct role for CD4+ T cells mediating tumor control in the setting of metastatic disease in human cancers has been seen in individual and small cohorts of patients." (PMID 36159781, 2022). "There was elevated T cells infiltration at early stage of tumorigenesis in the tumor site along with up-regulated percentage of memory CD4+, CD8+ T cells." (PMID 36761171, 2022). "We examined the expression levels of CD107a, a degranulation marker that shows cytotoxic activity against tumor cells in CD4+ and CD8+ T cells." (PMID 36611881, 2022). "Here, use of a low, vascular-normalizing dose of anti-VEGFR2 antibody led to increased tumor infiltration of CD4+ and CD8+ T cells and improved the efficacy of a cancer vaccine therapy in a CD8+ T cell-dependent manner in mouse breast cancer models." (PMID 36175961, 2022). "Interleukin-12 (IL-12) is a proinflammatory cytokine that initiates antitumor immune responses by promoting the generation of tumor-specific cytotoxic T lymphocytes (CTLs) and activating natural killer (NK) cells and CD4+ T cells." (PMID 35756634, 2022). "For immune cells, we found CD4 T cells, B cells and plasma cells were low infiltrated in tumor tissues, while the infiltration levels of Treg, monocytes and myeloid cells were increased, indicating an immunosuppressive phenotype." (PMID 36387901, 2022). "CD4 + T cells can kill tumors either directly by destroying the tumor cells or indirectly by mediating TME regulation." (PMID 36465903, 2022). "Second, the predominant effector type of CD4 T cells at the tumor site is relevant for cancer patient survival." (PMID 35903540, 2022). "CD4+ T cells are thought to have immune surveillance and antitumor effects, which have been found to recognize tumor cells and initiate their lysis." (PMID 36457551, 2022). "Our data demonstrate that co-treatment with ICB (αPD-L1) and tumor-specific CD4+ T-cell adoptive transfer can induce a tumor-specific CD4+ T lymphocyte proliferation response, which contributes to better tumor control." (PMID 35784297, 2022). "al, which proved that LAG-3 defines an active subset of CD4+CD25highFoxp3+ regulatory T cells whose frequency is increased in cancer patients and is spread at tumor sites." (PMID 36077354, 2022). "T cells, B cells and NK cells can all have their activation and proliferation suppressed by CD4+ Treg and CD4+ Treg can also attract MDSCs in the tumor stroma." (PMID 36439472, 2022). "This resulted in increased CD8+ T-cell infiltration, Th1 polarisation of CD4+ T-cells, and M1 macrophage differentiation in the tumours of microbially ablated mice, correlating with an enhanced anti-tumour immune response." (PMID 35205769, 2022). "Although, CD8+ T lymphocytes (CD8 TL) have been considered to be the main protagonists, due to their cytotoxic activity on tumor cells, it is now clear that CD4+ T lymphocytes (CD4 TL) also play a critical role in orchestrating the antitumor immune response." (PMID 35546670, 2022). "Flow cytometric data exhibited that lncRNA HOXA-AS2 silencing led to a significantly lower ratio of CD4+CD25+Foxp3+ cells in the tumor tissues." (PMID 35181676, 2022). "Activated memory CD4+ T-cells and follicular helper T cells are archetypal anti-tumor immune cells, as we all know." (PMID 35399509, 2022). "In the tumor microenvironment, TAMs are capable of presenting tumor antigens to effector CD4 T cells." (PMID 35903540, 2022). "This observed tumor weight difference translates into functional relevance based on CD4 IFNγ levels, and hence, we categorized the CD4 IFNγ high expression group as responders and the CD4 IFNγ low expression group as non-responders to the ITI-1001 treatment." (PMID 35651802, 2022).
tumor (continued). "This emphasizes the role of CD4 T cells in the initiation phase of the anti-tumor response that is delayed but fully functional after CD4 T-cell depletion." (PMID 34584204, 2022). "CD4+ and myeloid populations colocalized within the tumor parenchyma, while CD8+ T cells and B cells were peripherally dispersed." (PMID 36313703, 2022). "We showed for the first time, that live-attenuated Listeria vaccine reduced the expression of several important tumor-promoting ICIs on CD4/CD8 T lymphocytes." (PMID 35173308, 2022). "Examples of the output from the EPIC algorithm showing the relative abundance of B, natural killer (NK), CD4+ T and CD8+ T cells, macrophages, and cancer-associated fibroblasts (CAFs) in a selection of tumour samples are shown." (PMID 36498899, 2022). "Our study showed increased FoxP3 expression and higher CD4+/CD8+ ratios in CD27+ tumor infiltrating lymphocytes surrounding CD70+ tumor cells in NSCLC patients." (PMID 34991665, 2022). "We used the double staining of CD20 and CD8 or CD4 to highlight infiltrated T-lymphocyte in tumor tissues." (PMID 36606194, 2022). "This occurs within the TME and in the draining lymph nodes, resulting in tumor infiltration by CD4+ and CD8+ T cells." (PMID 35804917, 2022). "CD4+ T cells exhibit developmental plasticity and can directly kill tumor cells, but they eliminate tumor cells at the slower rate and release the lower levels of Granzyme B than CD8+ T cells." (PMID 35757715, 2022). "qRT-PCR further showed that the expression of those genes was significantly increased in circulating CD4+ T cells (> 80% neoplasm cells) from the SS patient compared to those from advanced-stage MF patients, PE patients, and HCs." (PMID 36400759, 2022). "Compared with treatment naïve tissues, the gene expression results of tumor-derived CD4+ and CD8+ T cells after ADT treatment, showed downregulated in similar pathways, among which IFN response related pathways ranked high in both groups." (PMID 36506053, 2022). "Lymphocyte-activation gene 3 (LAG-3) is a cell surface marker predominantly expressed in CD3-positive T cells with low expression in normal or malignant B cells, NK cells, and myeloid cells 35 and in PD-1-positive CD8+ and CD4+ tumor-infiltrating lymphocytes." (PMID 35223381, 2022). "There were higher proportions of CD4 T lymphocytes (Th) compared to CD8 T lymphocytes (Tc) in the tumour tissue (P = 0.0006)." (PMID 35975974, 2022). "Even if cytotoxic CD8+ T cells play a leading role in the killing of tumor cells, CD4+ TH cells are also very important and highly potent T cells." (PMID 35203517, 2022). "More specifically, it was found that ILK expression is negatively correlated with tumor purity in COAD, LUSC and STAD which in turn reflected significant positive associations with infiltration of CD4+ T cells, macrophages, neutrophils and DCs." (PMID 35692780, 2022). "The mechanisms of OVs involve direct oncolytic activity and the promotion of the immunogenic cell death of tumor cells, generating a tumor-reactive T cell response, especially for CD4+ and CD8+ T cells." (PMID 35214129, 2022). "In the original study, the authors also revealed that the trends of increased CD8+ and decreased CD4+ T cells were similar, which is performed by immunohistochemistry on paired normal and tumor tissue." (PMID 35812372, 2022). "A number of studies demonstrated that STING agonists combined with a cancer vaccine or delivery platform induced a potent inflammatory response and modulated the tumor microenvironment by increasing proliferation of CD4+ T cell." (PMID 36298450, 2022). "CD4+ T cells can recognize tumor antigens, supporting the initiation and expansion of CD8+ T cells in lymphoid tissues." (PMID 35603183, 2022). "This demonstrated that in the stroma of PDLIM2-positive and PDLIM2-negative tumours the percentages of CD4+, CD8+ or Foxp3+ T cells present in all tissues and stroma were similar, regardless of PDLIM2 expression." (PMID 36531051, 2022).
tumor (continued). "On the other hand, there are other factors related to tumor immunity such as CD4+ lymphocytes which recognize major histocompatibility complex class II cancer antigen of dendritic cells and induce several immune reactions." (PMID 35137571, 2022). "These cells also produce modest levels of cytokines during exhaustion, tumor-infiltrating T CD4+ cells with high levels of PD-1 and CD39 release considerable quantities of cytokines." (PMID 37305016, 2022). "CD4+ T cells are much more effective in stimulating host immune responses to prevent tumor relapse than CD8+ T cells after immunotherapy." (PMID 35874660, 2022). "In tumor-bearing animals, IL-27 downregulated the expression of FoxP3 in CD4+ and CD8+ T cells and prevented generation and expansion of Tregs, immunosuppressive T cells which inhibited antitumor immunity in IL-10- and TGF-β-dependent manner." (PMID 35757015, 2022). "The importance of antigen-specific CD4 T cells in producing a robust anti-tumor response that was identified in our studies stands to inform future antigen-specific vaccination efforts." (PMID 36385142, 2022). "The CD4:CD8 ratio was 1.1 within tumor tissue prior to chemotherapy but fell to 0.65 following NACT." (PMID 36253784, 2022). "The immune cells within tumor microenvironment from all samples were confirmed to express CD4 and CD8 on immune cell membranes, and FOXP3 on nucleus of immune cells by IHC examination." (PMID 35963999, 2022). "Previous studies proved that reprogramming of the tumor immune microenvironment was a valuable prognostic signature, such as a lack of T cells, microphage phenotype, the number of B cells, CD4+ T cells, CD8+ T cells, DC cells, and the ablation of eosinophils." (PMID 35464857, 2022). "Impaired ability to produce IFN-c and IL-2 was exhibited by the majority of tumor-derived TIM-3+ CD4 T cells, and in vitro, they significantly suppressed the proliferation of autologous CD8+ T cells." (PMID 36359346, 2022). "Increased level of tumor infiltrating CD4+ and CD8+ T cells and decreased level of myeloid-derived suppressor cells (MDSC) were observed in the tumors of the combination treatment group, compared with monotherapy." (PMID 35710296, 2022). "cDCs1 exert the most potent anti-tumor functions resulting from the ability to release IL-12 and orchestrate anti-tumor CD8+ T cell effectors functions, through cross-presentation and induction of anti-tumor CD4+ Th1 type cells." (PMID 36338516, 2022). "Their expression was associated with tumor infiltration by immune cells, such as macrophages, neutrophils, B cells, CD8+ T cells, CD4+ T cells, and DCs." (PMID 35874675, 2022). "Tumor-infiltrating proliferating conventional and regulatory CD4 T cells were positively correlated with increased E2F signaling as well as hypoxic and glycolytic gene signatures." (PMID 35662283, 2022). "CD3+/CD8+ T cell is a main cell population of cytotoxic T cell capable of killing various types of tumor cells, while CD4+/CD25+ T cell is considered a kind of regulatory T cell (Treg) inhibiting the activation of cytotoxic T cell." (PMID 35692503, 2022). "In the current study, infiltration of most of the anti-tumor immune cells, such as CD4 T cells, CD8 T cells, natural killer T cells, follicular helper T cells, and type 1 T helper cells, was observed in m6A cluster A and high m6A score groups." (PMID 35528542, 2022). "Preliminary analysis showed that of the patients who received ADT followed by docetaxel and then PROSTVAC, 31%, 50%, and 50% had CD4/CD8 responses to tumor antigens PSA, MUC-1, and brachyury, respectively." (PMID 36497086, 2022). "It has also been shown that the loss of Ikaros expression was associated with a significant decrease in CD4+ and CD8+ T cell percentages but increased CD4+ CD25+ Tregs in tumor-bearing mice." (PMID 36009534, 2022). "Since the current study setting lacks tumor-specific CD4+ T cells, an increased cDC1 to cDC2 ratio induced by TBI in the spleen was a better prognostic factor." (PMID 36497152, 2022).
tumor (continued). "Concomitantly, the proportions of CD4+ T helper cells were lower compared to the healthy controls and stage I tumor patients, whereas that of CD8+ cytotoxic T cells was progressively higher." (PMID 36428793, 2022). "Conversely, activation of CLEC7A can exert effective anti-tumor immunity by enhancing the expression of interleukin-33 and interleukin-9 in dendritic cells and by inducing differentiation of naive CD4+T cells into T-helper 9 cells." (PMID 35480896, 2022). "Collectively, our results support the idea of an antigen-driven stimulation of CD4+ Th TILs at the tumor site that leads to local activation and expansion of DP CD4+ cells." (PMID 35439168, 2022). "E6/E7-based vaccination can remarkably increase splenic and tumor IFN-γ-producing CD4+ and CD8+ T cells." (PMID 36300095, 2022). "In our model, both CD8+ and CD4+ T-cell populations had been reduced in tumour-bearing animals after SID, indicating that a reduced T-cell associated anti-tumour immune response induced by trauma due to surgery is not related to the primary tumour." (PMID 36010845, 2022). "Previous work suggested that MHC class I-restricted TCRs with high functional avidity were CD8 coreceptor independent, which directed CD4+ T cells to produce typical Th1 cytokines and cytotoxic proteins for tumor elimination." (PMID 35928827, 2022). "Then the mice tumor tissues were taken to analyze the expression levels of CD4+ T and CD8+ T cells by flow cytometry." (PMID 35705974, 2022). "In our study, JX-594 effectively remodeled the TME both in the primary tumors and distant lung metastatic sites through the activation of the immune system, which increased the tumor-infiltrating CD4/8+ T cells and DCs." (PMID 35052851, 2022). "Baseline levels of tumor-infiltrating CD4+ T cells, inflammatory cytokines and immune checkpoints have all been turned out to be correlated with the likelihood of an immune response." (PMID 36408192, 2022). "Prior studies have shown that the breadth of the T cell landscape in NSCLC is closely tied with tumor mutational burden, marked by an increased proportion of dysfunctional CD8+ and CD4+ T cell subsets." (PMID 36733391, 2022). "Further, when applying spatial analysis using Measure B, i.e., excluding any peritumoral stroma, encapsulated metastases demonstrated a higher CD8/CD4 ratio at the tumor margin and up to 400 μm towards the tumor center (p < 0.05)." (PMID 35158957, 2022). "In a colon cancer model, IL-33 can increase interferon (IFN)-γ production by tumor-invasive CD4+ and CD8+ T cells." (PMID 35464435, 2022). "The results of the Tumor Immune Estimation Resource (TIMER) database indicated that the expression of RFCs was negatively correlated with the infiltration of CD4+ T cells and macrophages." (PMID 35483337, 2022). "To further confirm that this enhanced tumor cell death was T cell‐dependent, we depleted the CD4/8pos T cells together with the CD15pos cells." (PMID 35611994, 2022). "Our study supports previous, and arguably understated, findings showing the crucial roles played by both IFNγ signaling on host cells and antigen presentation by TAMs for CD4-mediated tumor rejection." (PMID 35903540, 2022). "The meta-analysis of pre-clinical data revealed that Gf usage upon cancer treatment significantly inhibited tumor growth, and, on the contrary, improved remission rates, and also increased CD4+ and CD8+ T cell percentages, as well as IL-2, IL-12, and TNF-α." (PMID 35890166, 2022). "These CD4+ T cells kill autologous tumours in a major histocompatibility complex class II (MHCII)-dependent manner and are suppressed by Tregs." (PMID 36159866, 2022). "The collagen family genes, for instance, were independently related to the survival of NMIBC and were simultaneously recognized as the DEG of tumor-infiltrating B cells, CD4+ T cells, CD8+ T cells, DCs, CAFs, macrophages, and endothelial cells." (PMID 35719408, 2022).
tumor (continued). "TOP1MT is associated with tumor purity, B cells, CD8+ T cells, CD4+ T cells, macrophages, neutrophils, and dendritic cells in various cancers." (PMID 36035140, 2022). "Previous studies in our laboratory and others have demonstrated that a high-salt (HS) diet induces inflammatory activation of CD4+T cells leading to anti-tumor responses." (PMID 35741331, 2022). "In a previous study, CD39+CD73+ tumor cells reduced the proliferation of CD4+ T and CD8+ T cells by CD39 and the adenosine dependent pathway, and treatment with CD39 inhibitors or blocking antibodies reduced the tumor-induced inhibition." (PMID 36268017, 2022). "A decrease in levels of most tumor-infiltrating immune cells (TIICs) like CD4+T, CD8+T, NK, dendritic cells, and macrophages was observed in cluster C2." (PMID 36518754, 2022). "In contrast, the quantity of regulatory T lymphocytes (Tregs; CD3+CD4+CD25+) in the tumor tissues was significantly decreased in the 25 mW micro-LED-treated group." (PMID 36258234, 2022). "JHU083 treatment decreases immune suppressive cells, including both monocytic‐ and granulocytic‐myeloid‐derived suppressor cells, regulatory T cells, and pro‐tumor CD4+ Th17 cells in mouse models." (PMID 35861366, 2022). "In H22 tumor-bearing mice, STRGD inhibited telomerase activity and reduced the number of CD4+CD25+ regulatory T cells to inhibit tumor growth and increase body weight, thus improving the general condition of the mice." (PMID 35754689, 2022). "Mice depleted of CD4 T cells in addition to Tregs showed a delayed tumor regression compared with Treg depletion-control (C violet)." (PMID 34584204, 2022). "MHC II aAPCs also relay help signals from CD4+ T cells to tumor-specific CD8+ T cells, which, in turn, enhance CD8+ T cell cytokine production, memory formation, and in vitro and in vivo antitumor activity." (PMID 36241639, 2022). "Activated immune cells, especially tumor-infiltrating lymphocytes such as CD4+ cells, CD8+ T cells, and NK cells were abundant in cluster A. In addition, immunomodulators, which are essential for cancer immunotherapy, showed significant disparities." (PMID 35558555, 2022). "We found that depletion of either CD8+ or CD4+ T cells abrogated tumor control and survival benefits mediated by mito + oHSV + ICI therapy." (PMID 35163675, 2022). "Effector CD8+ T cells, together with Th1 CD4+ T cells, are major players in the anti-tumour response." (PMID 35454848, 2022). "Among them, memory CD4+ T cells are reported to play a crucial role in anti-tumor responses to LUAD." (PMID 35620481, 2022). "A high percentage of CD4+ tumor-infiltrating lymphocytes in the tumor stroma is correlated with a worse prognosis." (PMID 36118863, 2022). "The quality of a T cell response—for CD8+ or CD4+ cells—is determined by the recognition of a specific target antigen presented on a major histocompatibility complex (MHC) on the surface of the tumor cell via the cognate TCR." (PMID 36077730, 2022). "The results showed that all LILRB family members were significantly associated with tumor purity, B cells, CD8+ T cells, CD4+ T cells, macrophages, neutrophils, and dendritic cells." (PMID 35321724, 2022). "High pyroscore was associated with high immune score, low tumor purity, and high infiltration of CD8+ T cells/CD4+ T cells/resting dendritic cells, which indicates that pyroptosis is associated with active immune environment." (PMID 35401536, 2022). "The expression of Ki-67 of tumor tissues in mice injected with CD4+ T LEX-CD8086 cell was 53.9%, which was significantly lower than that in the mice injected with CD4+ TLEX-null cell (73.5%) and LEX-CD8086 (69.8%) and control (93.4%)." (PMID 36466863, 2022). "The number of tumor-infiltrating CD4+, CD8+, Foxp3+lymphocytes, CD68+, CD163+macrophages in pre-treatment endoscopic biopsy samples were evaluated to investigate their predictive value for multidisciplinary treatment." (PMID 35658848, 2022).